NLRP3 (NLR family pyrin domain containing 3)
Diseases named in the same sentence as NLRP3 in open-access papers (continued):
Sharing a sentence is not in itself a finding about the gene and the disease.
metabolic disorders (continued). "It is worth stressing that T2DM has been the first metabolic disease shown to involve NLRP3." (PMID 33546399, 2021). "Whether autophagy can influence NLRP3 inflammasome by phosphorylating NLRP3 in metabolic disorders remains to be clarified." (PMID 33796528, 2021). "The role of NLRP3 inflammasome in the kidney under different metabolic disorders." (PMID 34305953, 2021). "The persistent activation of NLRP3 results in chronic inflammation, one of the key mechanisms in various metabolic diseases, which could be alleviated by ES-Exo." (PMID 35047512, 2021). "The NLRP3 inflammasome is a crucial step in innate immune responses and contributes to immune pathogenesis of several diseases including neurodegenerative, cardiac, pulmonary, gastrointestinal, and metabolic diseases." (PMID 34202842, 2021). "Together, these studies demonstrate how chronic and acute inflammatory and metabolic diseases can be exacerbated throughout the aging process, further complicating our understanding of the biology of the NLRP3 inflammasome and its role in the pathogenesis of diseases and aging." (PMID 32751530, 2020). "NLRP3 has also been reported to play an important role in diabetes and other metabolic diseases." (PMID 31178664, 2019). "The deficiency of such NLRP3 inflammasome-mediated gut defense response may block GLP-1 formation and release, thereby linking gut dysbiosis and metabolic disorders." (PMID 31632284, 2019). "The involvement of inflammasome pathways in the pathophysiology of central nervous system (CNS) diseases, metabolic disorders, and chronic inflammatory diseases is fostering research on the potential therapeutic benefits resulting from the pharmacological targeting of NLRP3 inflammasome." (PMID 31200447, 2019). "Furthermore, it has been reported that omega-3 PFAs block inflammation and metabolic disorder through inhibition of pyrin domain-containing 3 (NLRP3) inflammasome activation." (PMID 30992001, 2019). "To further confirm that TR prevents or treats metabolic disorders through inhibition of NLRP3 inflammasome activation, we tested whether TR treatment inhibited the NLRP3 inflammasome activation and metainflammation in diabetic mouse models." (PMID 29531021, 2018). "Therefore, controlling NLRP3 inflammasome activation is a promising therapy for the treatment of inflammatory diseases such as bacterial infections, neurological disorders, and metabolic disorders." (PMID 29163487, 2017). "We discuss the newly identified functions for NLRP3 in metabolic homeostasis, and how NLRP3 beneficial functions in homeostasis may become detrimental during the onset of inflammatory and metabolic diseases." (PMID 27551512, 2016). "While the innate immune response to insults can efficiently protect against disease and death, inappropriate activation of the NLRP3 inflammasome can contribute to the onset and progression of various diseases, particularly age-related diseases such as metabolic disorders and metabolic syndrome." (PMID 26594174, 2015). "NLRP3 gene silencing was insufficient to improve the systemic metabolism disorder." (PMID 25136835, 2014). "However, the NLRP3 gene silencing therapy had little effect on improving these systemic metabolic disorders." (PMID 25136835, 2014). "Thus, the NLRP3–IL-1β axis represents an important molecular link that translates metabolic excess into systemic inflammation and organ dysfunction in various tissues in metabolic diseases." (PMID 40943225, 2025). "Interestingly, we found that SA also could regulate the balance of gut microbiota and its metabolism disorder in NASH rats by inhibiting NLRP3/ASC/caspase-1 axis." (PMID 38026986, 2023). "To determine whether KA ameliorates metabolic disorders by inhibiting the activation of the NLRP3 inflammasome, we fed mice a high-fat diet (HFD) with or without KA supplementation for 14 weeks and then performed a glucose tolerance test (GTT) and insulin tolerance test (ITT)." (PMID 36311752, 2022).
metabolic disorders (continued). "Furthermore, omega-3 fatty acids and beta-hydroxybutyrate have been shown to prevent inflammation and metabolic disorders via inhibition of NLRP3 inflammasome activation, whereas MCC950, RRx-001, oridonin, and tranilast can directly target NLRP3 to alleviate inflammasome-driven diseases." (PMID 36379253, 2022). "A dysfunctional activation of the NLRP3 inflammasome leads to chronic inflammation, a common pathogenetic link between several conditions, including autoinflammatory, autoimmune, and infectious states, as well as degenerative and metabolic diseases and tumorigenesis." (PMID 36275641, 2022). "Thus, our study highlights that PPARγ agonism may be a therapeutic option for targeting NLRP3-related metabolic diseases." (PMID 33500734, 2021). "Interestingly, the development of NASH is closely related to metabolic disorders, suggesting that NLRP3 may be involved in NASH." (PMID 33692776, 2020). "It has been demonstrated that the NLRP3 pathway participates in a variety of important responses such as host defense, where its activity is beneficial, and the NLRP3 pathway also contributes to metabolic diseases, where it may play a pathophysiological role." (PMID 26498951, 2016). "The goal of this paper is to review new insights on the effects of the NLRP3 inflammasome activation in the complex mechanisms of crosstalk between different organs, for a better understanding of the role of chronic inflammation in metabolic disease pathogenesis." (PMID 23843683, 2013). "In vivo, ECG alleviated metabolic disorders in OVX mice by reducing lipid accumulation, attenuating inflammatory responses, and inhibiting NLRP3 inflammasome activation." (PMID 41169786, 2025). "In conclusion, high starch could not only induce metabolic disorders via gluconeogenesis and accumulation of glycogen, TAG, and cholesterol, but could disturb redox homeostasis and cause inflammatory responses by activating the NLRP3 inflammasome in largemouth bass." (PMID 38668364, 2024). "In summary, these results revealed that sodium butyrate inhibited autophagy and NLRP3 inflammasome activation by blocking the PI3K/Akt/NF-κB pathway, thereby alleviating oxidative stress, inflammation, and metabolic disorder induced by AGEs." (PMID 36557849, 2022). "A number of exogenous and endogenous signals might act as NLRP3 inflammasome activator in AT leading to the production of pro-inflammatory cytokines a potential mechanism linking an elevated intake of saturated fatty acids (SFAs) to the progression of metabolic diseases." (PMID 33809891, 2021). "When activated, NLRP3 inflammasome triggers the release of pro-inflammatory interleukins (IL)-1β and IL-18, an essential step in innate immune response; however, defective checkpoints in inflammasome activation may lead to autoimmune, autoinflammatory, and metabolic disorders." (PMID 33435142, 2021). "We subsequently found that sEVs derived from steatotic liver promote NLRP3 inflammasome-dependent microvascular endothelial hyperpermeability, suggested that hepatic sEVs might be an independent pathogenic factor of CMD independent from the metabolic disorders during NAFLD." (PMID 34838052, 2021). "However, recent studies underscore the link between NLRP3-mediated inflammation and cellular metabolism — a metabolically triggered inflammatory state known as “metainflammation,” which is a form of chronic, low-grade inflammation accompanying metabolic disorders." (PMID 32750036, 2020). "Therefore, NLRP3-dependent pyroptosis and maturation of pro-inflammatory effectors (IL-1β/IL-18) induced by ROS could contribute to development of autoimmune and even metabolic diseases, such as DCM." (PMID 28790925, 2017). "The NLRP3 inflammasome, activated via ROS accumulation, exhibited elevated ASC levels and arrhythmic expression in the SD + SiNPs-treated ELGs, mirroring findings in neurodegenerative and metabolic disorders." (PMID 40890823, 2025).
metabolic disorders (continued). "Therefore, SA can improve NASH by regulating the NLRP3/ASC/caspase-1axis, its related intestinal flora composition, and metabolic disorder." (PMID 38026986, 2023). "We demonstrate that KA specifically prevents NLRP3 inflammasome activation by mitigating calcium mobilization and mitochondrial damage and mitochondrial ROS production via GPR35, which improves inflammatory diseases and metabolic disorders." (PMID 36311752, 2022). "As for the mechanism of NLRP3 activation during ALD, it has been elucidated that the metabolic disorders of uric acid and ATP induced by alcohol could lead to mitochondrial damage, and the activation of NLRP3 inflammasome." (PMID 36389791, 2022). "Although the interplay between autophagy and NLRP3 inflammasome has potential therapeutic value in metabolic disorders, its mechanism has not been fully explained." (PMID 33796528, 2021). "MAM, on the other hand, plays an important role in innate immune cell response to ER stress and serves as a site of NLRP3 inflammasome activation under stress conditions, implying that MAM could serve as a novel potential therapeutic target for inflammatory‐related metabolic diseases." (PMID 35759226, 2022). "However, the therapeutic effects of Ori on metabolic disorders were absent in Nlrp3-/- mice." (PMID 29959312, 2018). "Recently, one study described that monounsaturated and polyunsaturated fatty acids could impede the NLRP3 inflammasome activation in metabolic diseases 49, but it was not clear whether CYPs/COX-2 were involved in the activation of NLRP3 inflammasome." (PMID 32308747, 2020).
kidney diseases (157 papers, 2011 to 2025). "Damage to lysosomes is frequently associated with various kidney diseases, and the NLRP3 inflammasome also plays a crucial role in this pathological process." (PMID 40841164, 2025). "Activation of the NLRP3 inflammasome has been implicated in multiple mouse models and human kidney diseases, including AKI and CKD." (PMID 38907332, 2024). "Consistent with earlier reports, the progression of kidney disease in diabetic rats was associated with the perturbation of the NLRP3 inflammasome signaling axis." (PMID 37237918, 2023). "We observed similar results in the adenine-induced kidney disease models with genetic deletion of Acss2 or Fasn, suggesting that NLRP3 inflammasome activation is associated with kidney disease development in these models." (PMID 38051585, 2023). "The NLRP3 inflammasome has been associated with the development of fibrosis in several diseases, including kidney disease." (PMID 34769294, 2021). "NLRP3 inflammasome activation mediated by Damage-associated molecular patterns (DAMPs) such as extracellular matrix components and ROS in several renal diseases was previously reported." (PMID 34904012, 2021). "The NLRP3 inflammasome has been implicated in the pathogenesis and progression of LN and other kidney diseases." (PMID 34830358, 2021). "The most extensively studied component of the NLRP3 inflammasome associated with kidney disease is IL-18." (PMID 33215255, 2021). "The protective effects of PD against NLRP3 activation in kidney disease have been reported; however, the mechanism underlying this effect has yet to be fully elucidated." (PMID 32131850, 2020). "Increasing evidence has demonstrated that ER stress and Nlrp3 inflammasome activation are important pathogenic factors in multiple kidney diseases." (PMID 27721575, 2016). "Nod-like receptor pyrin domain-containing-3 (NLRP3) has been implicated in the pathogenesis of experimental renal injury, yet its characterization in human kidney disease remains largely unexplored." (PMID 27093923, 2016). "Inhibition of NLRP3 inflammasome activation could attenuate podocyte injury and improve renal function in kidney diseases caused by various factors, such as inflammation and lipid metabolism in DN." (PMID 36874000, 2023). "Furthermore, children with proteinuria and diverse underlying kidney diseases showed significantly higher NLRP3 protein expression compared to healthy control subjects, and a significant correlation between tubular NLRP3 expression and severity of proteinuria." (PMID 35204131, 2022). "Moreover, studies have suggested that NLRP3 can also mediate the inflammatory response and is strongly associated with kidney disease." (PMID 34693876, 2021). "Several components of the NLRP3 inflammasome have been implicated in renal disease." (PMID 24450291, 2014). "Moreover, lysosomal damage, potentially leading to the release of lysosomal calcium (Ca2+), is implicated in the activation of the NLRP3 inflammasome, further illustrating the complex interplay of cellular events leading to inflammatory responses in renal disease." (PMID 39104818, 2024). "Additionally, the NLRP3 inflammasome has been associated with the activation of other cell death mechanisms, including apoptosis and necroptosis, further highlighting its involvement in renal disease pathogenesis." (PMID 37371054, 2023). "In view of their important findings and based on our data, we infer that the pathogenic role NLRP3 plays very likely in the initial or accelerating/progressing stages of the renal disorder, although further investigations are required to validate the hypothesis." (PMID 28117341, 2017). "Numerous biological inhibitors targeting the NLRP3 inflammasome have been developed to date; however, their efficacy and safety profiles in the context of kidney diseases remain to be fully established." (PMID 41357229, 2025). "In recent years, P2X7R-induced NLRP3 activation has garnered immense attention in the field of kidney disease." (PMID 40520155, 2025).
kidney diseases (continued). "Targeting NLRP3 for kidney disease therapy has transitioned from the stage of “proof-of-concept” to the critical phase of “precision translation”." (PMID 41357229, 2025). "In summary, significant progress has been made in elucidating the functional roles of the NLRP3 inflammasome in kidney diseases." (PMID 41357229, 2025). "The NOD-like receptor protein 3 (NLRP3) inflammasome has been verified in multiple animal models of kidney diseases, including UUO, hypertensive kidney injury, diabetic kidney disease, glomerulonephritis, and 5/6 nephrectomy." (PMID 40520155, 2025). "PNS and NLRP3 inflammasome have shown promising results in the treatment of kidney disease through these modes of action." (PMID 40841164, 2025). "Several investigational agents targeting the NLRP3 inflammasome or its downstream effectors have already shown encouraging results in non - renal diseases; however, research evaluating their efficacy specifically in kidney pathologies remains limited." (PMID 41357229, 2025). "Our data suggest a potential therapeutic strategy for the treatment of renal diseases by targeting the gut microbiota and the NLRP3 inflammasome." (PMID 38907332, 2024). "The role of NLRP3 inflammasomes in different types of renal macrophages in kidney disease remains to be explored." (PMID 38740765, 2024). "And NLRP3 inhibitors can significantly improve proteinuria and renal function in mice, underscoring the importance of the NLRP3 inflammasome in kidney disease." (PMID 38347570, 2024). "The NLRP3–ASC–caspase-1–IL-1β–IL-18 pathway has been identified as a factor in the development of the pathophysiology of numerous kidney diseases." (PMID 38740765, 2024). "By regulating the abundance of intestinal flora to activate FUNDC1-mediated mitochondrial autophagy and inhibit NLRP3-mediated inflammation, we can adjust the homeostasis of intracellular environment and treat renal disease." (PMID 39445333, 2024). "Among these targets, the canonical activation of NLRP3 inflammasome was shown to be involved in kidney diseases, mainly by the regulation of necroinflammation." (PMID 37627536, 2023). "Previous studies demonstrated that NLRP3 is a key sensor of cell injury and is expressed in proximal tubular epithelial cells in kidney disease." (PMID 37901251, 2023). "TRIM40 also has associations with IgA nephropathology, which causes kidney disease; it is thought to suppress IgA1-induced GMC proliferation by inhibiting the activation of NLRP3 inflammasome." (PMID 37759668, 2023). "It has been reported that the levels of NLR family pyrin domain–containing 3 (NLRP3) inflammasome and other inflammasome-related genes are upregulated in human kidney diseases." (PMID 37581942, 2023). "In different experimental renal diseases, the genetic or pharmacological inhibition of NLRP3 has demonstrated beneficial effects." (PMID 37627536, 2023). "As an initial member of the inflammasome activation, NLRP3 is involved in the pathophysiology of numerous renal diseases in both inflammasome-dependent and inflammasome-independent ways." (PMID 37759588, 2023). "Although the role of NLRP3 inflammasome activation in renal damage has been extensively studied, to the best of our knowledge only a few studies have investigated the association of NLRP3 and CARD8 genetic variants with a susceptibility to kidney disease." (PMID 36835594, 2023). "The significance of NLRP3 inflammasome activation in renal diseases lies in its contribution to the pathogenesis and progression of various renal conditions." (PMID 37371054, 2023). "In recent years, the pathological role of NLRP3 inflammasome in renal disorders has drawn substantial attention." (PMID 37237918, 2023). "Mounting evidence indicates that NLRP3 has important effects on several kidney diseases, including pyelonephritis and IgA nephropathy." (PMID 37901251, 2023).